UBE2D4 (ubiquitin conjugating enzyme E2 D4)
Description:
Accepts ubiquitin from the E1 complex and catalyzes its covalent attachment to other proteins. In vitro able to promote polyubiquitination using all 7 ubiquitin Lys residues, but may prefer 'Lys-11' and 'Lys-48'-linked polyubiquitination.
Synonyms: HBUCE1
Tractability: Antibody: the Human Protein Atlas places it where antibodies can reach. PROTAC: ubiquitination databases record sites on it.
Gene: Protein-coding gene on chromosome 7 (43,926,436 to 43,956,136, forward strand). Ensembl gene ENSG00000078967.
Subcellular location (Human Protein Atlas): Cytosol; Plasma membrane
Pathways (Reactome):
Immune System: Antigen processing: Ubiquitination & Proteasome degradation
Gene Ontology:
Molecular function: protein binding; ubiquitin conjugating enzyme activity; ubiquitin-protein transferase activity
Biological process: protein K11-linked ubiquitination; protein K27-linked ubiquitination; protein K29-linked ubiquitination; protein K48-linked ubiquitination; protein K6-linked ubiquitination; protein K63-linked ubiquitination; protein ubiquitination; ubiquitin-dependent protein catabolic process
Genetic constraint (gnomAD): Loss-of-function variants: 15 observed, 21.81 expected, observed/expected ratio (o/e) 0.69, 90% interval 0.46 to 1.06. The upper end of that interval is the gene's LOEUF score, 1.06, which puts it in group 4 of 6, group 1 being the genes least tolerant of losing a copy. Missense variants: 127 observed, 176.63 expected, observed/expected ratio (o/e) 0.72, 90% interval 0.62 to 0.83. Synonymous variants: 59 observed, 68.99 expected, observed/expected ratio (o/e) 0.86, 90% interval 0.69 to 1.06.
Homologues: Orthologues: chimpanzee UBE2D4 (100% identical), zebrafish ube2d4 (99% identical), tropical clawed frog ube2d4 (93% identical), pig UBE2D4 (84% identical), guinea pig UBE2D4 (75% identical). Paralogues in human: UBE2D2 (93% identical), UBE2D3 (91% identical), UBE2D1 (90% identical), UBE2E1 (64% identical), UBE2E2 (64% identical), UBE2E3 (64% identical), UBE2L5 (41% identical), UBE2L3 (40% identical), UBE2L6 (39% identical), UBE2Q1 (32% identical), UBE2Q2 (32% identical), UBE2QL1 (27% identical).
Diseases named in the same sentence as UBE2D4 in open-access papers:
UBE2D4 is named in the same sentence as 7 diseases in open-access papers, as found by Europe PMC text mining. Sharing a sentence is not in itself a finding about the gene and the disease. The quoted sentences say what the papers report.
retinal degeneration (2 papers, 2024 to 2025). Degeneration of the retina. "To this purpose, we expressed human UBE2B (homologous to Ubc6, DIOPT homology score = 13) and human UBE2D2 and UBE2D4 (homologous to eff, DIOPT scores of 13 and 10, respectively) and compared their capacity to rescue retinal degeneration compared to mock mcherry overexpression." (PMID 39879147, 2025). "On this basis, we expressed human UBE2B (homologous to Ubc6, DIOPT homology score=13) and human UBE2D2 and UBE2D4 (homologous to eff, DIOPT scores of 13 and 10, respectively) and compared their capacity to rescue retinal degeneration compared to mock mcherry overexpression." (PMID 38168249, 2024).
breast carcinoma (1 paper, 2019). "High expression of CSNK2B (p = 0.0041, HR = 1.37), GRPEL1 (p = 0.0200, HR = 1.29) and QARS (p = 0.0350, HR = 1.26) were corelated with worse prognosis in breast cancer patients, whereas CCND3, HDAC3, SH3BGRL3, SRM, and UBE2D4 were not correlated with OS." (PMID 31781497, 2019).
Sepsis (1 paper, 2024). Sepsis is defined as life-threatening organ dysfunction caused by a dysregulated host response to infection. "Finally, the 6 DECuGs (ANKRD9, DLD, LIPT1, MTF1, PDHB, UBE2D4) as diagnostic biomarkers for sepsis were identified by the intersection of the two machine learning algorithms." (PMID 38495196, 2024). "Next, six key DECuGs (ANKRD9, DLD, LIPT1, MTF1, PDHB, UBE2D4) were identified as diagnostic biomarkers based on the two machine learning algorithms, suggesting their potential functional importance in the pathogenesis of sepsis." (PMID 38495196, 2024). "For immune cells, monocytes, T cells, B cells, and NK cells were related to DLD, LIPT1, MTF1, PDHB and UBE2D4 in the sepsis group." (PMID 38495196, 2024).
UBE2D4 also shares sentences with these, for which no sentence is quoted: acute leukemia (1 paper); cancer (1); myopia (1); tumor (1).